KIRREL2 (kirre like nephrin family adhesion molecule 2)
Description:
May regulate basal insulin secretion.
Synonyms: NEPH3; NLG1; FILTRIN; DKFZp564A1164; MGC15718
Tractability: Antibody: its Gene Ontology location is reachable by antibodies, with high confidence; UniProt places it where antibodies can reach, with medium confidence; UniProt predicts a signal peptide or a membrane-spanning region. PROTAC: ubiquitination databases record sites on it.
Gene: Protein-coding gene on chromosome 19 (35,851,369 to 35,867,145, forward strand). Ensembl gene ENSG00000126259.
Subcellular location: Cell membrane
Subcellular location (Human Protein Atlas): Centriolar satellite
Pathways (Reactome):
Cell-Cell communication: Nephrin family interactions
Gene Ontology:
Molecular function: protein binding; cell adhesion molecule binding; identical protein binding
Biological process: cell adhesion; cell-cell adhesion
Cellular component: centriolar satellite; cell-cell junction; membrane; plasma membrane; slit diaphragm
Genetic constraint (gnomAD): Loss-of-function variants: 52 observed, 62.93 expected, observed/expected ratio (o/e) 0.83, 90% interval 0.66 to 1.04. The upper end of that interval is the gene's LOEUF score, 1.04, which puts it in group 4 of 6, group 1 being the genes least tolerant of losing a copy. Missense variants: 858 observed, 880.75 expected, observed/expected ratio (o/e) 0.97, 90% interval 0.92 to 1.03. Synonymous variants: 397 observed, 388.94 expected, observed/expected ratio (o/e) 1.02, 90% interval 0.94 to 1.11.
Homologues: Orthologues: chimpanzee KIRREL2 (99% identical), dog KIRREL2 (90% identical), pig KIRREL2 (89% identical), guinea pig KIRREL2 (87% identical), mouse Kirrel2 (84% identical), rabbit KIRREL2 (83% identical), rat Kirrel2 (83% identical), macaque KIRREL2 (77% identical), tropical clawed frog kirrel2 (42% identical), zebrafish kirrel3l (42% identical), Drosophila melanogaster kirre (27% identical), Caenorhabditis elegans syg-1 (24% identical), and 4 more. Paralogues in human: KIRREL1 (37% identical), KIRREL3 (36% identical), NPHS1 (24% identical).
Diseases named in the same sentence as KIRREL2 in open-access papers:
KIRREL2 is named in the same sentence as 15 diseases in open-access papers, as found by Europe PMC text mining. Sharing a sentence is not in itself a finding about the gene and the disease. The quoted sentences say what the papers report.
cerebral amyloid angiopathy (1 paper, 2023). "It would be interesting if Kirrel2 localizing at the boundary between neighboring PV-AEF of arteries/arterioles is involved in cerebral amyloid angiopathy." (PMID 37829206, 2023).
diabetes (1 paper, 2024). "In the nonobese diabetic mouse model during the pathogenesis of diabetes, the progressive decline in the expression of KIRREL2 was observed." (PMID 39314522, 2024).
pancreatic cancer (1 paper, 2014). "The panel of promoter CGIs in this study included KIRREL2 and SLC13A5, which have previously been identified as the differentially-methylated CGIs in pancreatic cancer and cloned using methylated CpG island amplification-representational difference analysis from pancreatic cancer cell lines." (PMID 25289081, 2014).
infection (2 papers, 2024). The state of being infected such as from the introduction of a foreign agent such as serum, vaccine, antigenic substance or organism. "When comparing DEG in both SARS-CoV-2-infected groups at day 2 (i.e., 2 days after SARS-CoV-2-only infection and 4 days after H1N1 infection in the dual-infected group), only five known genes (Cd3d, Ctsw, Kirrel2, Osbpl1a and Aurkb) were differentially expressed at padj < 0.05." (PMID 38400021, 2024).
tumor (2 papers, 2022 to 2023). "If a more ‘MBGrp3‐like’ position upon the continuum, exemplified by high levels of KIRREL2 expression, denotes an ‘earlier’ developmental disruption, why should those tumours be more aggressive and difficult to treat?" (PMID 37021628, 2023). "The two following patterns of membranous-cytoplasmic KIRREL2 immunostaining were detected: (i) “Positive”—tumor sample was either patchily or entirely/diffusely stained." (PMID 35771282, 2022). "However, only KIRREL2 was differentially expressed between Grp 3 and other MB groups in both the current-screening and independent-validation tumor cohorts." (PMID 35771282, 2022). "Therefore, KIRREL2 overexpression in some Grp 3 MB may suggest their biological resemblance to mitotically active and poorly differentiated cerebellar neural progenitors thus partly explaining the clinical aggressiveness of this tumor subtype." (PMID 35771282, 2022).
cancer (1 paper, 2022). A tumor composed of atypical neoplastic, often pleomorphic cells that invade other tissues. "Overexpression of KIRREL2 at mRNA and/or protein level has been closely associated to advanced tumors stages, metastases development, drug resistance and poor prognosis of human cancers, although the underlying molecular mechanisms are still unclear." (PMID 35771282, 2022).
KIRREL2 also shares sentences with these, for which no sentence is quoted: nephrotic syndrome (2 papers); diabetic nephropathy (1); glomerular diseases (1); IgA nephropathy (1); kidney damage (1); medulloblastoma (1); nephrosis (1); renal disease (1); renal failure (1).